ENSG00000307409 (novel transcript)
Gene: Long non-coding RNA gene on chromosome 12 (75,870,278 to 75,884,841, reverse strand). Ensembl gene ENSG00000307409.
Gene Ontology:
Biological process: SRP-dependent cotranslational protein targeting to membrane, signal sequence recognition
Cellular component: signal recognition particle, endoplasmic reticulum targeting